NSUN5 (NOP2/Sun RNA methyltransferase 5)
Diseases named in the same sentence as NSUN5 in open-access papers (continued):
Sharing a sentence is not in itself a finding about the gene and the disease.
cancer (17 papers, 2019 to 2026). A tumor composed of atypical neoplastic, often pleomorphic cells that invade other tissues. "All cancers were highly positively associated with the writer gene NSUN5 and reader gene ALYREF synchronization." (PMID 36923798, 2023). "NSUN5, a gene encoding cytosine-5 RNA methyltransferase, has rarely been reported associated with cancer." (PMID 37263638, 2023). "The NSUN5 gene is a commonly mutated gene in many human cancers." (PMID 41536427, 2025). "NSUN5 is a conserved RNA methyltransferase whose oncogenic role has been demonstrated in various cancers." (PMID 41555554, 2026). "Existing basic experiments indicate that NOP1, NSUN2, NSUN3, and NSUN4 predominantly promote the majority of cancers, while NSUN5, NSUN6, and NSUN7 demonstrate context-dependent effects—promoting some cancers but inhibiting others." (PMID 41462962, 2025). "NSUN5 exhibited upregulation in many cancer types, indicating its potential role as a significantly oncogenic factor." (PMID 38182896, 2024). "Because protein synthesis is commonly deregulated in cancer to support their growth, we examined the functional impact of the elevated NSUN5 expression in GBM cells." (PMID 37057706, 2023). "The cancer patients with an overexpressed NSUN5 have a poorer prognosis, and this condition is positively correlated with NSUN5 translation." (PMID 36319976, 2022). "In this risk score signature, four genes (NOP2, NSUN4, NSUN5, and NSUN7) were cancer-promoting and NSUN6 was a cancer-suppressor gene." (PMID 32974125, 2020). "Once again, we can consider how cancer cells avoid death when confronted by damaging stress conditions, because, as we have shown for NSUN5, the disruption of IDH1 is another way of dealing with metabolic and hypoxic stress." (PMID 31428936, 2019). "NSUN5 found an increase in the number of copies in some cancers." (PMID 41536427, 2025). "A pan-cancer analysis of NSUN5 transcription, utilizing patient samples sourced from the Cancer Genome Atlas (TCGA) database, revealed dysregulation of its expression across various cancer types, including HCC." (PMID 38182896, 2024). "In addition to METTL5/TRMT112 complex, NSUN5 and snoRNAs, other key regulators also play significant roles in rRNA modifications and ribosome biogenesis, significantly influence cancer progression." (PMID 38797935, 2024). "Over the past decade, the oncogenic role of NSUN5 has been identified in several cancer types." (PMID 38182896, 2024). "Therefore, further studies are warranted to determine the role of NSUN5 in cancer to better understand the implication of NSUN5, and RNA cytosine methylations in general, in tumorigenesis." (PMID 37057706, 2023). "IHC confirmed that NSUN5 is localized in the nucleus of cancer cells in human GBM tissues." (PMID 37057706, 2023). "Thus far, only three studies on NSUN5 in cancer have been reported." (PMID 37057706, 2023). "Thus far, only three publications have addressed the role of NSUN5 in cancer." (PMID 37057706, 2023). "NSUN5 is generally upregulated in human cancers, including CRC, which may be attributed to the hypomethylation of NSUN5 promoter." (PMID 36319976, 2022). "Notably, most current studies focus on mRNA, but the modification of rRNA by NSUN5 and the modification of lncRNA and miRNA by NSUN2 suggest the potential of m5C modification of non-coding RNA for cancer development." (PMID 35562754, 2022).
cancer (continued). "Our study shows that NSUN5 is an RNA cytosine methyltransferase that mediates cytosine 3782 methylation of 28S rRNA and promotes protein synthesis and tumorigenic properties in GBM, providing additional support for the emerging role of RNA 5‐methylcytosine in cancer." (PMID 37057706, 2023).
infection (4 papers, 2019 to 2026). The state of being infected such as from the introduction of a foreign agent such as serum, vaccine, antigenic substance or organism. "The KEGG results from the CGGA and TCGA databases revealed that NSUN5 is closely associated with Epstein‐Barr virus infection, human immunodeficiency virus one infection, lysosome function, and proteasome." (PMID 41555554, 2026). "To exclude the possibility that the reduction of cell numbers was due to acute infection stress, we re-seeded one of the HDF strains at the same cell density and again, a decrease in proliferation upon NSUN5 depletion was evident." (PMID 31722427, 2019).
neurodevelopmental disorder (2 papers, 2014 to 2024). A behavioral and cognitive disorder with onset during the developmental period that involves impaired or aberrant development of intellectual, motor, or social functions. "NSUN5 is located in the deletion genome of a neurodevelopmental disorder called Williams‐Beuren syndrome, and the deletion of NSUN5 may be one of the pathogenic causes of the disorder." (PMID 39006762, 2024). "In humans the NSun5 gene is located to a genomic region deleted in patients with Williams–Beuren syndrome, a rare neurodevelopmental disorder and lack of NSun5 may contribute to the growth retardation, the myopathy or the premature aging effects reported for the syndrome." (PMID 25014650, 2014).
NSUN5 also shares sentences with these, for which no sentence is quoted: clear cell renal carcinoma (2 papers); brain tumors (1); breast tumors (1); cervical cancer (1); diffuse intrinsic pontine glioma (1); gastric cancer (1); head and neck cancer (1); lung adenocarcinoma (1); lung carcinoma (1); malignant glioma (1); medulloblastoma (1); mental retardation (1); myopathy (1); pancreatic cancer (1); pulmonary stenosis (1); soft tissue sarcoma (1); thyroid cancer (1).